CEACAM6 (CEA cell adhesion molecule 6)
Description:
Cell surface glycoprotein that plays a role in cell adhesion and tumor progression. Intercellular adhesion occurs in a calcium- and fibronectin-independent manner. Mediates homophilic and heterophilic cell adhesion with other carcinoembryonic antigen-related cell adhesion molecules, such as CEACAM5 and CEACAM8. Heterophilic interaction with CEACAM8 occurs in activated neutrophils. Plays a role in neutrophil adhesion to cytokine-activated endothelial cells. Plays a role in cell migration and cell adhesion to endothelial cells.
Synonyms: CD66c; NCA; NCA-50/90; CEAL
Tractability: Antibody: UniProt places it where antibodies can reach, with high confidence; its Gene Ontology location is reachable by antibodies, with high confidence; UniProt predicts a signal peptide or a membrane-spanning region.
Gene: Protein-coding gene on chromosome 19 (41,750,977 to 41,772,211, forward strand). Ensembl gene ENSG00000086548.
Subcellular location: Cell membrane; Apical cell membrane; Cell surface
Pathways (Reactome):
Extracellular matrix organization: Fibronectin matrix formation
Hemostasis: Cell surface interactions at the vascular wall
Immune System: Neutrophil degranulation
Gene Ontology:
Molecular function: identical protein binding; protein binding; protein heterodimerization activity
Biological process: heterophilic cell-cell adhesion; homophilic cell-cell adhesion; negative regulation of anoikis; positive regulation of cell migration; positive regulation of cell population proliferation; positive regulation of endothelial cell-matrix adhesion; positive regulation of heterotypic cell-cell adhesion
Cellular component: apical plasma membrane; cell surface; extracellular region; membrane; azurophil granule membrane; plasma membrane
Genetic constraint (gnomAD): Loss-of-function variants: 20 observed, 32.02 expected, observed/expected ratio (o/e) 0.62, 90% interval 0.44 to 0.91. The upper end of that interval is the gene's LOEUF score, 0.91, which puts it in group 3 of 6, group 1 being the genes least tolerant of losing a copy. Missense variants: 364 observed, 411.97 expected, observed/expected ratio (o/e) 0.88, 90% interval 0.81 to 0.96. Synonymous variants: 168 observed, 165.85 expected, observed/expected ratio (o/e) 1.01, 90% interval 0.89 to 1.15.
Homologues: Orthologues: chimpanzee CEACAM6 (99% identical), macaque CEACAM1 (79% identical). Paralogues in human: CEACAM1 (83% identical), CEACAM5 (81% identical), CEACAM8 (78% identical), CEACAM7 (50% identical), PSG8 (46% identical), PSG7 (45% identical), PSG6 (45% identical), PSG1 (44% identical), PSG4 (44% identical), PSG3 (44% identical), PSG9 (44% identical), PSG11 (40% identical), and 12 more.
Diseases named in the same sentence as CEACAM6 in open-access papers:
CEACAM6 is named in the same sentence as 148 diseases in open-access papers, as found by Europe PMC text mining. Sharing a sentence is not in itself a finding about the gene and the disease. The quoted sentences say what the papers report.
pancreatic cancer (38 papers, 2004 to 2025). "Most genes have been related to diabetes and cancer, with most of them being linked to pancreatic cancer (CEACAM6, HDAC5, HPCAL1, PARVG, and STYXL1)." (PMID 36360783, 2022). "In pancreatic cancer cells, CEACAM6 overexpression was associated with anoikis resistance and tumor metastasis in vitro and in vivo." (PMID 29137373, 2017). "Notably, CEACAM1, CEACAM5, and CEACAM6 have been found to be implicated in immune related disease and cancer, and are now considered valid clinical biomarkers and promising therapeutic targets in melanoma, lung, colorectal, and pancreatic cancers." (PMID 36741860, 2023). "CEACAM6 overexpression enhances pancreatic cancer-cell invasiveness and confers resistance to apoptosis and chemotherapy." (PMID 40282889, 2025). "Previous studies targeting CEACAM6 have shown promising results in disrupting tumor cell adhesion, promoting apoptosis, and overcoming chemoresistance mechanisms in preclinical pancreatic cancer models." (PMID 40282889, 2025). "Prior studies in gastric and pancreatic cancers have shown that CEACAM6 activates PI3K/AKT signaling, supporting the mechanistic overlap observed in our study." (PMID 40936892, 2025). "Background and Objectives: Carcinoembryonic antigen-related cell adhesion molecule 6 (CEACAM6) is involved in pancreatic cancer progression and is an attractive therapeutic target for pancreatic cancer." (PMID 40282889, 2025). "Among various cancer types, pancreatic cancer has been extensively studied in terms of CEACAM6 expression." (PMID 38796667, 2024). "Accordingly, here we show the potential efficacy of pancreatic cancer by CEACAM6-EBET ADC powered by its cancer-cell-killing activity, stromal modulation activity, and good antibody profile." (PMID 38467634, 2024). "CEACAM6 is highly expressed in hyperplastic polyps and colon adenomas, breast cancer, pancreatic cancer, mucinous ovarian cancer, gastric cancer, and lung adenocarcinoma." (PMID 36741860, 2023). "CEACAM5 was reported to function as an oncogene by promoting tumor progression and inducing anoikis resistance in colorectal cancer, while CEACAM6 was found to be involved in the metastatic process by inducing anoikis resistance in pancreatic cancer." (PMID 37090717, 2023). "Overexpression of miR-29a resulted in a significant decrease in the CEACAM6 protein levels, thereby inhibiting the migration and invasion of pancreatic cancer cells." (PMID 36522691, 2022). "Carcinoembryonic antigen-related cell adhesion molecule 6 (CEACAM6) was discovered as a possible promising pancreatic cancer biomarker." (PMID 34207784, 2021). "Poorer overall survival was significantly dependent on increased CEACAM6 blood serum concentrations (17.0 vs. 12.6 months, p = 0.017) in pancreatic cancer patients after radical treatment and adjuvant chemotherapy." (PMID 34207784, 2021). "Tissue markers that are differentially expressed in pancreatic cancer (CEA, mucin-1 (MUC-1)), mesothelin, mutated KRAS G12, CA19-9, carcinoembryonic antigen-related cell adhesion molecule 6 (CEACAM6) have been recently studied as potentials vaccine targets." (PMID 33546207, 2021). "It was proved that CEACAM6 overexpression has an effect on cellular invasiveness towards insulin-like growth factor I, which has a critical role in the malignant behaviour of pancreatic cancer cells." (PMID 34207784, 2021). "Since CEACAM6 possesses significant features for pancreatic cancer development, it was investigated as a potential treatment target." (PMID 34207784, 2021). "Similar to CEACAM5, CEACAM6 overexpression was considered a potential driving force of pancreatic cancer progression." (PMID 34663338, 2021). "In our study, we searched for a new improved biomarker for PDAC and identified and validated CEACAM6 expression predominantly in pancreatic cancer tissue samples." (PMID 34207784, 2021). "MiR‐29a/b/c specific for CEACAM6 can regulate its expression at the post‐transcriptional level in pancreatic cancer." (PMID 32648688, 2020).
pancreatic cancer (continued). "In a murine model of pancreatic cancer, administration of a CEACAM6-specific monoclonal antibody conjugated with immunotoxin increases tumor apoptosis and decreases tumor growth." (PMID 31211760, 2019). "Currently, CEACAM1, CEACAM5, and CEACAM6 are considered as valid prognostic markers and promising therapeutic targets in melanoma, lung, colorectal, and pancreatic cancers." (PMID 29137373, 2017). "Studies demonstrated that CEACAM6 is overexpressed in several human malignancies, including colorectal adenomas and carcinomas, gastric carcinomas, and pancreatic carcinomas etc.." (PMID 29137373, 2017). "Overexpression of cyclin D1/CDK4 is regulated by CEACAM6 and promotes cell proliferation in human pancreatic carcinoma." (PMID 27818681, 2016). "CEACAM6 has been considered a valid clinical biomarker and promising therapeutic targets in melanoma, lung, colorectal, and pancreatic cancers." (PMID 25938545, 2015). "A relatively high rate of CEACAM6-positive reactivity has been demonstrated in the sera of patients with lung cancer, hepatocellular carcinoma, pancreatic cancer, breast cancer, and colorectal cancer." (PMID 25427744, 2015). "Although negative correlation between CEACAM6 and EMT has been recorded in pancreatic carcinomas, the mechanisms by which CEACAM6 regulates EMT are poorly understood." (PMID 25398131, 2014). "Phosphorylated AKT levels were increased in CEACAM6-overexpressing cells, consistent with previous results noted in pancreatic carcinomas." (PMID 25398131, 2014). "CEACAM6-specific RNAi decreases cancer cell proliferation, metastasis and angiogenesis in pancreatic cancer." (PMID 23251258, 2013). "The present study provides a novel gene therapy strategy that is effective, not only for pancreatic cancer, but also for other CEACAM6-expressing tumors." (PMID 23251258, 2013). "The in vitro experiments on pancreatic carcinoma SW1990 cells were studied using a triple-gene vector expressing CEACAM6-shRNA and the fusion suicide gene yCDglyTK." (PMID 23251258, 2013). "Pancreatic carcinoma cell lines stably expressing the CEACAM6 shRNA and yCDglyTK gene were then established and anti-tumor efficacy of the recombinant plasmid was evaluated in vitro." (PMID 23251258, 2013). "The recombinant plasmid was delivered into SW1990 human pancreatic carcinoma cells, the mRNA and protein expression of yCDglyTK and CEACAM6 was examined by RT-PCR, western blot analysis and immunofluorescence." (PMID 23251258, 2013). "This semi-quantitative analysis is intended only as an initial step towards elucidating the importance of CEACAM6 as a tumor target in a variety of solid tumors that extend the many important studies reported for pancreatic cancer." (PMID 17201906, 2007). "Pancreatic cancer has been the most extensively studied neoplasm with respect to CEACAM6 expression." (PMID 17201906, 2007). "Study of anti-CEACAM6 immunotoxin-based therapy in mouse model of pancreatic carcinoma was published recently." (PMID 15826304, 2005). "CEACAM6 could enhance the binding between integrin αvβ3 on pancreatic cancer cells and the extracellular matrix, and promote integrin α5β1 on the colorectal cancer cells to bind to the fibronectin receptors of fibroblast cells." (PMID 36082960, 2023). "Various mechanisms of how CEACAM6 affects pancreatic cancer progression were already identified." (PMID 34207784, 2021). "The predominance of CEACAM6 to pancreatic cancer was validated using antibodies in tissue samples." (PMID 34207784, 2021). "This study validates CEACAM6 as a potential therapeutic target in pancreatic cancer." (PMID 31797958, 2019). "CEACAM6 has been successfully targeted in animal models of pancreatic cancer." (PMID 31211760, 2019). "Researchers also tested a single domain antibody targeting CEACAM6 that could be an ideal candidate for treating pancreatic cancer with CEACAM6 overexpression." (PMID 29137373, 2017).
pancreatic cancer (continued). "CEACAM6 expression appears to be an early event in the progression to pancreatic cancer." (PMID 25427744, 2015). "Additionally, overexpression of CEACAM6 enhancing metastasis invivo has also been reported in pancreatic cancer." (PMID 25398131, 2014). "CEACAM6 has also become a target for pancreatic cancer therapy." (PMID 23251258, 2013). "For example, CEACAM6 appears to affect the release of cytochrome-c from the mitochondria in response to cell detachment leading to the inhibition of caspase activation and hence, suppression of caspase induced apoptosis or anoikis in pancreatic cancer cells." (PMID 23021083, 2012). "Moreover, it has been previously reported that CEACAM6 can inhibit cytotoxicity induced by a conventional chemotherapeutic, gemcitabine, in pancreatic cancer cells." (PMID 23021083, 2012). "The highest expression of CEACAM6 in pancreatic tumors was found in moderately- (7.5 ± 0.7) > moderately-poor (5.9 ± 1.9) = well-moderately differentiated (5.8 ± 1.8) > poorly-differentiated tumors (5.1 ± 2.5) > well-differentiated (4.0 ± 0.0) adenocarcinomas (P = NS between the subtypes)." (PMID 17201906, 2007). "Thus, CEACAM6 is a promising new biomarker with significant prognostic value and prediction of chemoresistance properties, enabling the improvement of individualised approaches to patients with pancreatic cancer." (PMID 34207784, 2021). "Additionally, CEACAM6 was negatively correlated with EMT in pancreatic carcinomas and CEACAM6 suppression could increase E-cadherin promoter activity in colorectal cancer." (PMID 25398131, 2014). "Secondly, CEACAM6 has been shown to modulate the cytotoxic effects of conventional chemotherapeutics such as gemcitabine in pancreatic cancer cell lines and in the present study we showed that CEACAM6 could mediate sensitivity to new targeted agents such as the PI3K inhibitor, BGT226." (PMID 23021083, 2012). "An orthotopic pancreatic tumor model was generated using the murine PDAC cell line KPC961, which was engineered to express human CEACAM6 (hCEACAM6)." (PMID 38398062, 2024). "In pancreatic cancer cell lines PANC-1 and CFPAC-1, CEACAM6 is involved in the expression of epithelial to mesenchymal transition-associated genes ZEB1 and ZEB2, thereby increasing the metastatic potential of cells." (PMID 36741860, 2023). "For instance, CEACAM6 induces EMT and mediates invasion and metastasis in pancreatic cancer, gastric cancer via PI3K/AKT signaling pathway." (PMID 37249822, 2023). "We found that CEACAM6, JAM1, and integrin α3β1 are expressed at high levels and high frequencies in pancreatic carcinomas." (PMID 27834817, 2016). "It has also been demonstrated that the expression levels of CEACAM6 are higher than those of CEA in malignant tumors including breast cancer, lung cancer, prostate cancer, colon cancer, pancreatic cancer, and ovarian cancer." (PMID 25427744, 2015). "This study aimed to construct a recombinant plasmid pcDNA3.1(-) shCEACAM6-yCDglyTK from CEACAM6 targeting shRNA and the fusion suicide gene yCDglyTK for inhibition of SW1990 human pancreatic carcinoma cell growth and invasion." (PMID 23251258, 2013). "CEACAM6 appears to play a large part in regulating anoikis via a Akt/c-src signaling pathway and may regulate gemcitabine resistance in IHCC and pancreatic cancer." (PMID 38796667, 2024). "It was also reported that CEACAM6 expression was higher in pancreatic cancer with low differentiation than in medium differentiation, similarly, it was found that CEACAM6 expression was higher in tumor tissues than in adjacent normal tissues in colon cancer." (PMID 34221964, 2021). "Accordingly, CEACAM6 overexpression is seen in CRC and pancreatic cancer." (PMID 31211760, 2019). "Using this approach and verifying the data using individual gene expression data, we found that AGR2, CEACAM6, GNMT, PDIA2, POSTN, RBPJL, and S100P are upregulated in pancreatic tumor tissue as compared to non-tumor tissue from Black and White patients." (PMID 36812168, 2023).
breast carcinoma (35 papers, 2007 to 2025). "In breast cancer, CEACAM6 has been linked to paclitaxel resistance through PI3K/AKT pathway activation and apoptosis inhibition." (PMID 40936892, 2025). "CEACAM6 is a promising predictive biomarker in HR+/HER2− breast cancer, associated with chemoresistance and immune suppression." (PMID 40936892, 2025). "CEACAM6 emerged as a key gene significantly associated with overall survival in HR+/HER2- breast cancer." (PMID 40936892, 2025). "CEACAM6 expression has also been implicated in bone metastasis of breast cancer, and the coexpression of CEACAM6 and 8 inhibits the proliferation and invasion of breast cancer cells." (PMID 36035171, 2022). "Two stop gain mutations in CEACAM4 were associated with African American breast cancer, and two splicing mutations were associated with European American breast cancer, one in CEACAM6 and another within CEACAM8." (PMID 34447411, 2021). "Other metastases genes associated with poor prognosis in breast cancer, such as CEACAM6, COL17A1, CXCL8, TNFAIP3, SEMA7A and L1CAM, are also attenuated with SP receptor antagonist treatment." (PMID 34359773, 2021). "Associations between CEACAM6 positivity in breast cancer tissues and patient characteristics (n = 257)." (PMID 31331982, 2019). "We further confirmed that the PLA score of HER2/CEACAM6 was significantly associated with efficacy of HER2 inhibition after treatment with trastuzumab in breast cancer patients." (PMID 30326622, 2018). "High CEACAM6 expression was associated with breast cancer recurrence following adjuvant tamoxifen, and knockdown of CEACAM6 restored tamoxifen sensitivity and reduced clonogenic growth, migration, and invasion of tamoxifen-resistant MCF-7 cells." (PMID 29262572, 2017). "High expression of CEACAM5 and CEACAM6 has been associated with a variety of malignancies including breast cancer." (PMID 23285151, 2012). "For this, we have previously discovered new cell surface biomarkers, a carcinoembryonic antigen-associated cell adhesion molecule 6 (CEACAM6 or CD66c), of breast cancer-derived cancer stem cells (BCSCs) through omics-based analysis, which is the first report of its function in BCSCs." (PMID 36614128, 2022). "CEACAM6 has been shown to be a marker of atypical ductal hyperplasia lesions at increased risk of progressing to invasive breast cancer, and its expression is highest in ER+ and Her2+ breast cancers." (PMID 29262572, 2017). "CEACAM6 is a tumor-related gene that is involved in adhesion, migration, invasion, metastasis, apoptosis, and chemoresistance, although the implications of its loss in breast cancers is not well understood." (PMID 18221536, 2008). "For instance, CEACAM6 interacts with HER2 in breast cancer cells, and CEACAM6 knockdown reduces the inhibitory effects of the anti‐HER2 antibody trastuzumab in trastuzumab‐sensitive cells." (PMID 40856433, 2025). "In conclusion, our study identifies CEACAM6 as a potential biomarker of NAC response in HR+/HER2- breast cancer and implicates it in mediating immune evasion." (PMID 40936892, 2025). "Boxplot analyses revealed that MELK, BIRC5, and CEACAM6 were significantly overexpressed in HR+/HER2– breast cancer tissues compared to normal breast tissues in the TCGA cohort, whereas RARRES1 expression was markedly reduced in tumor tissues (p < 0.001)." (PMID 40936892, 2025). "Drug sensitivity analysis using the oncoPredict package revealed that high expression of CEACAM6 was associated with increased predicted IC50 values for several commonly used chemotherapeutic and endocrine agents in HR+/HER2− breast cancer." (PMID 40936892, 2025). "In breast cancer, CEACAM6 and CEACAM8 molecules are co-expressed to inhibit the invasion and proliferation of MCF-7 cells." (PMID 38796667, 2024). "Nevertheless, the complexity of the immunosuppressive landscape in pancreatic and breast cancers raises questions about the efficacy of antibody-mediated targeting of CEACAM6 in these malignancies." (PMID 38279989, 2024).